HIF1A (hypoxia inducible factor 1 subunit alpha)
Diseases named in the same sentence as HIF1A in open-access papers (continued):
Sharing a sentence is not in itself a finding about the gene and the disease.
tumor (continued). "We compared the in vitro effectiveness of mPDT vs. cPDT, evaluating the GBM cell viability, the PDT impact on the modulation of the phenotypic profile of the main non-tumor cell population of the tumor microenvironment (TME) and HIF-1α activation as an indirect indicator of oxygen consumption." (PMID 37296661, 2023). "Tumor regions without increased 18F-FDG uptake showed increased SLC13A5 and SLC16A1 expression, whereas tumors with increased 18F-FDG uptake showed high SLC2A1 and HIF1α." (PMID 35884416, 2022). "Interestingly, when compared to their individual tumor of origin and not as a cohort, primary cell cultures displayed an even slightly higher mRNA expression of CA9 and HIF1A, while the expression of VHL, VEGFA and VEGFC remained constant." (PMID 35646693, 2022). "Adding credence to our observation that HIF-1α promotes cytotoxicity in hypoxic NK cells is a study in a mouse tumor model with a targeted deletion of HIF-1α in NK cells, showing an increase in tumor metastasis due to reduced cytotoxicity of NK cells lacking HIF-1α." (PMID 34999917, 2022). "Furthermore HDACi is able to mediate HIF-1α proteasomal degradation independent of the pVHL pathway by promoting heat shock protein-70 (HSP70) expression, which ultimately impairs tumor growth." (PMID 36139386, 2022). "THPO, in turn, by stabilizing HIF-1α, induces VEGF-A dependent autocrine/paracrine loops, acting on VEGFR-2 expressing tumor, or on non-tumor cells that may affect HCC development and progression." (PMID 33673041, 2021). "In addition, the western blot results of tumor tissues also showed higher PDH and lower HIF-1α in NDUFS1 overexpressing groups combined with or without irradiation." (PMID 34489398, 2021). "Previous studies have shown that HIF-1A may regulate tumor angiogenesis, but in GBC and normal gallbladder controls, the relationship between cytoplasm HIF-1A expression, nuclear HIF-1A expression and MVD has not been studied." (PMID 33403040, 2021). "Moreover, oral gavage of 10 mg/kg of formononetin for 31 d significantly inhibited tumor growth in BALB/c mouse model inoculated with HeLa cells and reduced the expression of HIF-1α and VEGF in tumor tissues without severe side effects." (PMID 34680171, 2021). "In contrast to other tumor types, NDUFA4L2 expression in GBM may not be directly regulated by hypoxia-inducible factor (HIF)-1α, because HIF-1α inhibitors failed to inhibit NDUFA4L2 in GBM." (PMID 33828084, 2021). "When compared with tumor specimens from mice bearing colony not secreting IL-1β, MDA-MB-231 xenografts harvested from mice bearing colony secreting IL-1β exhibited a higher protein expression of HIF-1α." (PMID 34571989, 2021). "Moreover, overexpression of HIF-1α does not increase CRC tumorigenesis and does not result in spontaneous tumor formation in mice." (PMID 32351498, 2020). "Additionally, substantial accumulation of nuclear HIF-1α was observed in CCRCC, but not in non-tumor biopsies." (PMID 33339852, 2020). "It is important not to generalize because HIF-1α and HIF-2α may have different effect in other tumor cell lines." (PMID 32322559, 2020). "In some dogs with adenocarcinomas, tumor recurrence might not be influenced by Foxp3+ Tregs, VEGFR2 or HIF‐1α, and may effectively take advantage of other critical microenvironmental factors." (PMID 32267594, 2020). "Unlike HIF-1α, HIF-2α also plays a major role in the tumor cytoplasm." (PMID 32854260, 2020). "CAV1 expression in cancer cells reduces HIF1α transcriptional activity in hypoxia by reducing HIF1α S-nitrosylation and, as a consequence, the transcription of VEGF, which likely limits tumor growth and contributes to the tumor suppressor function of CAV1 in the absence of E-cadherin." (PMID 32825247, 2020).
tumor (continued). "Proviral insertion in murine lymphomas 2, a protein kinase acting as an oncogene, has been shown to phosphorylate PKM2 at Thr454, which facilitates the transcriptional co-activation of HIF-1α and β-catenin transcription factors to promote non-glycolytic nuclear function of PKM2 and tumor growth." (PMID 33292198, 2020). "Since the HIF-1α protein is an important negative factor for tumor radiotherapy, which is elevated after IR, we next tested whether MCL exerted radiosensitizing effect via inhibiting HIF-1α pathway." (PMID 32403326, 2020). "Of note, one-way ANOVA and Bonferroni's post hoc test of immune response and hypoxia-inducible indicators showed that the percentage of HIF1α and density of CD8+ and CD8+SATB1+ were significantly higher in stroma than in the tumor compartment (p < 0.0001) (data not shown)." (PMID 32612954, 2020). "However, despite the fact that N‐acetylcysteine prevented Hif‐1α stabilization under hypoxia in vitro, it did not reduce in vivo the tumor growth or the survival of EO771 tumor‐bearing mice but rather, increased the metastatic burden." (PMID 33026171, 2020). "Notably, we neither found any correlations between the PD-L1 expression (both on immune cells and on tumor cells [TPS]) and tumor hypoxia parameters nor between the PD-L1 expression and the tested hypoxia tissue markers CAIX and HIF1α." (PMID 32802199, 2020). "MCF7-HIF1α (−/−) showed no tumor growth in nonobese diabetic severe combined immunodeficient (SCID)-γ (NSG) mice, indicating that HIF-2α did not compensate for the absence of HIF-1α." (PMID 31152137, 2019). "To confirm the high expression of HIF-1α and TGF-β in vivo, we analyzed data of The Cancer Genome Atlas (TCGA) HCC cohorts and found that TGFB1 and HIF1A expression were significantly overexpressed in 371 tumor specimens compared with 50 non-tumor tissues." (PMID 31819036, 2019). "The metabolic remodelling in a tumour niche is endured not only by cancer cells but also by noncancerous cells that share the same microenvironment; in particular, macrophages seem to increase aerobic glycolysis via AKT/mTOR and HIF‐1α stabilization." (PMID 30499165, 2019). "Interestingly, the antibodies to HIF1A and LGMN also labeled some tumor cells, whereas anti-CD163 and anti-CD68 did not." (PMID 31434729, 2019). "However, HIF-2α, but not HIF-1α, can overcome VHL's tumor suppressor activity and eliminating HIF-2α is sufficient to suppress tumor formation." (PMID 29560117, 2018). "To determine whether the CT inhibited the expression of STAT3, SIRT3, HIF‐1α, GLUT1, LDHA, and HK2 in vivo, we performed qRT‐PCR to detect these genes expression in tumor tissues from the mouse with or without the treatment of CT." (PMID 30094960, 2018). "Furthermore, we show that this occurs in part, but not solely, through HIF-1α regulation of VEGF-A; and that VEGF-A in effector CD8+ T cells contributes to T cell infiltration, tumor vascularization, and tumor progression." (PMID 29136509, 2017). "HIF-1α, but not HIF-2α, drives CD8+ T cell glycolytic metabolism, migration, and effector function, while the HIF-1α transcriptional target VEGF-A contributes to tumor vascularization." (PMID 29136509, 2017). "Interestingly, one glycolytic gene (ENO2) was significantly increased in radiochemotherapy‐treated tumor tissue (Fig EV2D), and the glycolytic regulator HIF1A was increased but not to the same level of significance." (PMID 28183841, 2017). "However, the consequences of the lack of HIF-1α in such tumors is not to be neglected, especially in the light of studies demonstrating that inhibition of HIF-1α is sufficient to block tumor growth." (PMID 29230384, 2017). "In IFN-γ-stimulated tumor cells exposed to a DUOX2-specific siRNA, however, in addition to a lack of DUOX2 expression and decreased HIF-1α expression, we observed diminished ERK and S6 activation (compare lane 4 to lane 2) as well as no phosphorylation of 4E-BP1." (PMID 27637085, 2016).
tumor (continued). "Unlike HIF-1α, HIF-2α protein was significantly lower in tumor than in peritumoral tissues." (PMID 27119229, 2016). "Therefore, we postulate that hypoxia fails to stabilize HIF1α in tumor infiltrating T cells due to their higher OXOPHOS metabolism, triggered by PD1 signaling, and the nutrient composition in the tumor microenvironment." (PMID 26885366, 2016). "Importantly, not all cultured PDAC CAFs exhibited high HIF1α and MCT4 levels nor does all tumor stroma exhibit high levels of CAIX and MCT4; therefore indicating the presence of stromal diversity." (PMID 27623078, 2016). "HIF1α is mainly regulated at the protein level by the ubiquitin proteasome pathway, whose activation depends on the oxygen level, or by the activation of PI3K/AKT and MAPK signaling in a tumor, which is independent of oxygen level." (PMID 25896712, 2015). "Of interest, a previous report indicated that expression of CXCL8 might preserve the angiogenic response in HIF-1-inhibited tumor cells, suggesting that the NFκB pathway is important for the induction of CXCL8 in the absence of HIF-1α." (PMID 26696754, 2015). "Tumor burden measured by weight or luciferase activity were substantially reduced for ACSS2 and HIF-2α depleted cells, but not for control or HIF-1α depleted cells." (PMID 25689462, 2015). "Moreover, transcripts of HIF-1α and corresponding gene targets (glycocytic and nonglycocytic) were reduced in three of four BCSC subpopulations relative to tumor." (PMID 26316122, 2015). "However, studies have shown HIF1A and HIF2A to be non-redundant, to activate distinct transcriptional targets and to promote different tumour growth." (PMID 24837709, 2014). "Furthermore, we tested expression of genes of the Wnt and the HIF-1α/VEGF signaling pathways, which are known regulators of EC differentiation during embryogenesis and tumor growth (29, –, 31) (data not shown)." (PMID 24356956, 2014). "In tumor cells MME and HIF-1α staining were not strongly related." (PMID 24460801, 2014). "In addition to the observed lack of correlation between HIF-1α and CXCR4 protein expression within individual tumor samples, culture of cell lines under hypoxic conditions did not affect CXCR4 surface expression." (PMID 23249693, 2012). "Seemingly in contrast, our results instead demonstrate that chaetocin is cytotoxic in many tumour cell lines under normoxic in vitro conditions where HIF-1α is not upregulated or detectable, clearly indicating that HIF-1α is not required for its in vitro cytotoxicity." (PMID 22187030, 2012). "While therapeutic inhibition of HIF-1α has the potential to reduce the expression of a range of HIF-1 target genes, small molecule inhibition of transcription factors in vivo is inherently difficult and the tumour-specificity of HIF-1α inhibition is not clear." (PMID 22128892, 2011). "Thus, unlike HIF-1α that has a half-life measured in minutes, the prolonged half-life of CAIX means it would remain in the tumour when other proteins with a shorter half-life are no longer present." (PMID 21291529, 2011). "CAIX, HIF-1α, and Ki-67 expression levels observed in the TMA spots faithfully reflected the staining intensity of these proteins in whole-tissue sections from corresponding tumour blocks in a subset of 40 tumours (κ=0.89; data not shown)." (PMID 20461082, 2010). "Importantly, in normal SVZ cells, chemically HIF-1α stabilization was only transiently inducing REDD1 upregulation and Akt/mTOR pathway was not inhibited, unlike in tumor cells, following BMP2 treatment, and Akt and Stat3 were eventually upregulated." (PMID 19587783, 2009). "However, all 12 of the tumours with CYGB MtI⩾0.25 had relatively low levels of CYGB mRNA expression and this was irrespective of significant variations in HIF1A expression." (PMID 19568272, 2009).
tumor (continued). "However, there is increasing evidence for the functional non-equivalence of HIF-1α and HIF-2α, and in cancer, several recent studies have indicated that, at least in certain settings, they have contrasting effects on tumour growth." (PMID 17387348, 2007). "Furthermore, a substantial number of lymph node metastases corresponding to primary tumours positive for CA9 or Hif-1α, did not express CA9 or Hif-1α." (PMID 16251878, 2005). "However, down-regulation of HIF1α and GLUT1 are not the only impacts of mTORC1/2 inhibition: whilst MLN0128 monotherapy has marked effects on tumour growth in the KLLUC model, rapamycin fails to effect tumour growth." (PMID 40069402, 2025). "Hence, exogenous lactate stabilizes HIF-1α by acting as a substrate for pyruvate production, and a high lactate concentration in the TME ensures the transcriptional activation of tumor-promoting genes in all tumor cells regardless of oxygen supply." (PMID 36050306, 2022). "Infection of reovirus-permissive tumor cells and reovirus-resistant tumor cells with reovirus has been shown to significantly downregulate HIF-1α protein levels, which also occurred with UV-inactivated virus, indicating that downregulation of HIF-1α was independent of virus replication." (PMID 33135539, 2020). "Our current observation that HIF-1α and HIF-2α are present in the osteoclasts of some osteolytic tumours in the absence of marked expression of HIF in surrounding stromal cells led us to investigate whether HIF is induced during the differentiation of human osteoclasts." (PMID 33273561, 2020). "HIF-1α expression in liver metastasis, but not primary CRC, is correlated with poor prognosis of patients with CRLM, and HSCs might play a key role in the aggressive phenotype of tumor cells." (PMID 32895059, 2020). "Indeed, both HIF-1α and VEGF are significantly up-regulated in Non-Responders, indicating that the tumor microenvironment in Non-Responders may already be hypoxic prior to TACE, or may lead to an enhanced response to hypoxia induced during TACE." (PMID 31754337, 2019). "In the absence of oxygen, HIF-1α binds to hypoxia-response elements, thereby activating the expression of multiple hypoxia-response genes, including VEGF-A, which is produced by a majority of tumor cells, is present in the serum of cancer patients and whose expression is increased by RT." (PMID 28348554, 2017). "Furthermore, we showed herein that tumour levels of the thrombotic marker plasminogen activator inhibitor 1 (PAI1), and tumour levels of the tissue factor signalling receptor protease activated receptor 2 (PAR2), were positively correlated with HIF2α but not HIF1α levels." (PMID 28302670, 2017). "Similarly, Vascular Endothelial Growth Factor (VEGF), a tumor-derived factor, tended (p = 0.061) to be increased in BCa patients; while other putative tumor-derived factors such as RANK-L, Hypoxia-inducible Factor 1 alpha (HIF1α) or TNF-α were not significantly altered." (PMID 29113405, 2017). "Surprisingly, staining for HIF-1α and HIF-2α in tumours did not vary between normoxic and hypoxic preincubation, indicating that HIF-1/2α levels might not be the most adequate markers to detect previous hypoxic episodes experienced by tumour cells." (PMID 25664931, 2015). "Importantly, normal SVZ cells responded in a different way; indeed, by chemically stabilizing HIF-1α, REDD1 was transiently upregulated and Akt/mTOR pathway was not inhibited, unlike in tumor cells, following exposure to high oxygen tension, and Akt and Stat3 were eventually upregulated by CoCl2." (PMID 19587783, 2009). "Although, a modest recovery of HIF-1α protein was visible after 2 hr of high oxygen exposure in GBM cells, but not in normal cells, indicating that tumour cells may re-establish HIF-1α level through a hypoxic independent mechanism, possibly controlled by mTOR progressive activation." (PMID 19587783, 2009).
tumor (continued). "Although hypoxia-inducible factor 1 alpha (HIF-1α) is a major regulator of tumor cell adaptation to hypoxic stress, increasing the expression of glycolytic enzymes and proteins, the FDG uptake was not predictive for tumor hypoxia as assessed by pO2-polarography in our series of patients." (PMID 17598907, 2007). "Moreover, the CISH and IHC analyses confirmed that in the internal tumour region, the APCDD1L-AS1-knockdown group exhibited remarkably fewer APCDD1L-AS1 and DLST- positive cells than the control group, while no significant change was observed in HIF-1α-positive cells." (PMID 40634956, 2025). "Importantly, such transcription repression under hypoxia was retained even in the absence of HIF-1α or HIF-1β, supporting that the HIF-independent epigenetic regulation of gene expression would also substantially influence hypoxic responses and can thus be targeted for overcoming tumor hypoxia." (PMID 38730681, 2024). "HIF1A-mediated LEP upregulation in an LKB1-depleted environment may augment the LUAD energetic burden via activation of downstream mitochondrial uncoupling players such as UCP2; however that regulation alone does not appear sufficient to confer lethality to LKB1 tumours." (PMID 39048991, 2024). "This can explain the antitumorigenic effects of HIF-1α in cancers with low MYC oncogenic dependency and demonstrates the complexity of HIF-α in highly MYC oncogenic cancers, suggesting that solely inhibiting HIF-1α may result in preliminary attenuation, but have no impact on overall tumor burden." (PMID 35267567, 2022). "Intracellular lactic acid could inhibit the degradation of hypoxia inducible factor -1 alpha (HIF-1α) in endothelial cells under no hypoxia state and significantly increase VEGF and fibroblast growth factors produced by endothelial cells thus promoting tumor angiogenesis." (PMID 30627541, 2018). "This adds strength to the argument that HIF-1α is not the only protein that plays a role in LSCC carcinogenesis; HIF-1α may play an active role in the progression of malignancy, but other proteins may be required to accelerate tumor development and aggressiveness." (PMID 27882053, 2016).